TRBV7-4 (T cell receptor beta variable 7-4)
Description:
V region of the variable domain of T cell receptor (TR) beta chain that participates in the antigen recognition. Alpha-beta T cell receptors are antigen specific receptors which are essential to the immune response and are present on the cell surface of T lymphocytes. Recognize peptide-major histocompatibility (MH) (pMH) complexes that are displayed by antigen presenting cells (APC), a prerequisite for efficient T cell adaptive immunity against pathogens. Binding of alpha-beta TR to pMH complex initiates TR-CD3 clustering on the cell surface and intracellular activation of LCK that phosphorylates the ITAM motifs of CD3G, CD3D, CD3E and CD247 enabling the recruitment of ZAP70. In turn ZAP70 phosphorylates LAT, which recruits numerous signaling molecules to form the LAT signalosome. The LAT signalosome propagates signal branching to three major signaling pathways, the calcium, the mitogen-activated protein kinase (MAPK) kinase and the nuclear factor NF-kappa-B (NF-kB) pathways, leading to the mobilization of transcription factors that are critical for gene expression and essential for T cell growth and differentiation. The T cell repertoire is generated in the thymus, by V-(D)-J rearrangement. This repertoire is then shaped by intrathymic selection events to generate a peripheral T cell pool of self-MH restricted, non-autoaggressive T cells. Post-thymic interaction of alpha-beta TR with the pMH complexes shapes TR structural and functional avidity.
Synonyms: TRBV74; TCRBV6S8A2T; TCRBV7S4
Gene: T-cell receptor variable (V) gene on chromosome 7 (142,455,174 to 142,455,635, forward strand). Ensembl gene ENSG00000253409.
Subcellular location: Cell membrane
Gene Ontology:
Biological process: cell surface receptor signaling pathway
Cellular component: plasma membrane
Homologues: Paralogues in human: TRBV7-6 (81% identical), TRBV7-7 (79% identical), TRBV7-2 (70% identical), TRBV7-3 (70% identical), TRBV7-1 (69% identical), TRBV7-9 (68% identical), TRBV11-1 (58% identical), TRBV11-2 (57% identical), TRBV11-3 (57% identical), TRBV12-4 (55% identical), TRBV12-5 (54% identical), TRBV12-3 (53% identical), and 39 more.
Diseases named in the same sentence as TRBV7-4 in open-access papers:
TRBV7-4 is named in the same sentence as 2 diseases in open-access papers, as found by Europe PMC text mining. Sharing a sentence is not in itself a finding about the gene and the disease. The quoted sentences say what the papers report.
breast carcinoma (1 paper, 2022). "Thus far, the relationship of TNN, TRBV7-4, and PCP2 with cancer has not been reported, and our results suggest that these genes, as core pyroptosis genes, have important associations with breast cancer development and the immune microenvironment." (PMID 36158689, 2022).
TRBV7-4 also shares sentences with these, for which no sentence is quoted: cancer (1 paper).